TNF (tumor necrosis factor)
Diseases named in the same sentence as TNF in open-access papers (continued):
Sharing a sentence is not in itself a finding about the gene and the disease.
periodontitis (continued). "Ligature‐induced periodontitis and diabetic models: liraglutide decreases bone loss, improves microarchitecture, and lowers IL‐6, TNF‐α, and IL‐1β." (PMID 41328144, 2025). "The pro-inflammatory cytokines (IL-1, IL-6, and TNF-α) have been implicated in stimulating osteoclastic resorption in periodontitis." (PMID 41289041, 2025). "The TNF-α promoter polymorphism at −308 (G>A, rs1800629) has been extensively investigated in periodontitis." (PMID 41300760, 2025). "Shared molecular pathways can lead to LGSI, where the overproduction of ROS and pro-inflammatory mediators such as TNF-α and IL-6 negatively impact periodontal tissues, increasing susceptibility to the onset and progression of periodontitis." (PMID 41284085, 2025). "The participation of IL-17, together with TNF-α, in the pathogenesis of bone loss in periodontitis has already been suggested." (PMID 41021535, 2025). "Aggregatibacteractinomycetemcomitans which causes aggressive periodontitis triggered significant elevations of two major cytokines IL-1βand TNF-α." (PMID 40978611, 2025). "An anti-inflammatory effect is associated with vitamin D treatments, reducing serum levels of RANKL, TNF-α, and IL-1 and lowering alveolar bone loss in animals with periodontitis." (PMID 41149095, 2025). "While our findings demonstrate a significant reduction in IL-6 and TNF-α in the CO group, these two markers represent just a fraction of the inflammatory processes underlying periodontitis." (PMID 40085302, 2025). "The treatment with TNF‐α inhibitor had a significant adjunctive effect to periodontal therapy in the reduction of alveolar bone loss in the combined model of periodontitis and psorasis." (PMID 40277096, 2025). "For example, carriers of the TNF-α -308 G > A allele are more susceptible to apical periodontitis, leading to persistent periodontitis and maintaining the body in a state of chronic inflammation." (PMID 41244040, 2025). "P. gingivalis, the prime causative pathogen of periodontitis, raises serum IL-8 and TNF-α, linking periodontitis and GDM." (PMID 41394354, 2025). "ROC curve analysis revealed that combinations of CTRP-1, TNF-α, and IL-10 exhibited excellent diagnostic accuracy in differentiating periodontitis and gingivitis from a healthy condition." (PMID 40542868, 2025). "This strip enables simultaneous detection of three biomarkers associated with periodontitis—namely, interleukin-1 beta (IL-1β), tumor necrosis factor-alpha (TNF-α), interleukin-8 (MPP-8), and interleukin-1 beta (GCF)." (PMID 38183090, 2024). "This study focused on measuring the pro-inflammatory cytokines TNF-α, IL-1β, IL-6, and IL-8, pivotal not only in periodontitis but also in cancer-associated chronic inflammation." (PMID 38612423, 2024). "Elevated BMI, waist circumference, and body fat are strongly associated with increased risks of periodontitis, with inflammatory mediators such as TNF-α and IL-6 playing critical roles." (PMID 39796559, 2024). "A decrease in osterix mRNA and an increase in tumor necrosis factor-alpha (TNFα) were also observed, indicating their potential as diagnostic markers for periodontitis." (PMID 38610017, 2024). "This suggests that Pepper Elder extract effectively reduces the levels of TNF-α and IL-1β, mitigating tissue damage and alveolar bone loss, which are hallmark features of periodontitis." (PMID 39539670, 2024). "Oral administration of Cur can relieve bone absorption caused by periodontitis and reduce the expression of interleukin-4 (IL-4) and tumor necrosis factor-α (TNF-α) in the gingiva." (PMID 38549147, 2024). "Periodontitis is thought to cause low-grade systemic inflammation due to the production and release of inflammatory markers, including TNF-α and IL-6, into the bloodstream, which negatively affect endothelial function." (PMID 39062000, 2024). "VDR gene polymorphisms and TNF-α gene polymorphisms have been strongly associated to the occurrence of chronic periodontitis." (PMID 38699683, 2024).
periodontitis (continued). "Along with IL-6, other proinflammatory cytokines (IL-1, IL-8 or TNF-α) are also associated with osteoclast generation, leading to the development of periodontitis symptoms and/or associated diseases." (PMID 38791469, 2024). "Studies in C57BL/6 mice have demonstrated that periodontitis is associated with increased chronic inflammation, particularly elevated levels of TNF-α and tissue infiltration of Th17 cells and IL-17 + γδ T cells." (PMID 39203574, 2024). "Periodontitis is an inflammatory disease, and inflammatory factors such as IL-1, IL-6 and TNF-α are directly associated with periodontitis." (PMID 39124790, 2024). "Tacrolimus, a calcineurin inhibitor, has been demonstrated to protect against the inflammation-induced tissue and bone loss associated with periodontitis in experimental rats and oral diseases through a mechanism involving IL-1β, TNF-α, and IL-6." (PMID 37435641, 2024). "Th22 cells are a subpopulation of T-helper cells that produce IL-22 and TNF, which have been linked to the pathogenesis of periodontitis by increasing inflammation and the number of Th17 cells in periodontal lesions." (PMID 38919613, 2024). "CRP is a marker of acute or systemic inflammation, which is released in response to different cytokines (such as IL-6, IL-1, and TNF-α) associated with periodontitis." (PMID 36651310, 2023). "TNFα, a pro-inflammatory cytokine released by macrophages, is known for its extensive role in periodontitis-mediated bone loss." (PMID 36599866, 2023). "Oral epithelium disruption caused by development of periodontitis results in release of inflammatory cytokines, such as TNF and IL-1 β." (PMID 37674208, 2023). "The statistical analysis shows that IL-6 and nitric oxide were the biomarkers that showed the greatest value of significant association with periodontitis (P < 0.00001), accompanied by IL-1B (P < 0.0001), TNF-α (P = 0.004) and osteoprotegerin (P = 0.01)." (PMID 37026605, 2023). "To better understand the role of TNF-α in periodontitis, we examined its expression in a P.g-associated ligature-induced periodontitis model." (PMID 37232780, 2023). "Cytokines that are frequently associated with periodontitis are IL-1β, IL-6, IL-12, IL-16, IL-17, IL-21, and TNF-α." (PMID 37106750, 2023). "In fact, observational studies that investigated the association between TNF inhibitors and periodontal clinical parameters included patients diagnosed with periodontitis along with inflammatory diseases." (PMID 36845132, 2023). "In the matter of immunity regulation and osteoclastogenesis via the RANKL-OPG axis, vitamin D and TNF-α are pivotal in the pathogenetic analysis of bone-loss disorders associated with inflammation, including periodontitis." (PMID 37885557, 2023). "Previous investigations have revealed that CRP plays a vital role in the development of periodontitis, a significant cause of tooth loss, by causing the production of inflammatory mediators, such as IL-1, IL-6, and TNF-α." (PMID 38066835, 2023). "More specifically, proinflammatory cytokines such as TNF-α, IL-1, and IL-6 have been implicated in the activation of osteoclastic bone resorption in periodontitis." (PMID 37214190, 2023). "Several polymorphism studies in periodontitis including matrix metalloproteinase 3, interleukin 16 (IL-16), IL1α, and tumor necrosis factor α (TNFα) have been carried out." (PMID 38169768, 2023). "Periodontitis is associated with caspase and proinflammatory mediators, such as caspase-1 and tumor necrosis factor-alpha (TNF-α)." (PMID 36794778, 2023). "In the fifth study, significantly elevated levels of salivary cytokines, including interleukin (IL)-1β, IL-6, and tumor necrosis factor-alpha (TNF-α), were observed in periodontitis patients and strongly associated with clinical parameters." (PMID 38192959, 2023). "PFD inhibits alveolar bone loss and the expression of IL-1β, IL-6, and TNF-a in ligature-induced periodontitis in mice." (PMID 37240020, 2023).
periodontitis (continued). "The inflammatory biomarkers associated with OSA and chronic periodontitis include interleukin (IL)-1, IL-6, IL-8, tumor necrosis factor-α (TNF-α), and high-sensitivity C-reactive protein (hs-CRP)." (PMID 36915270, 2023). "Periodontitis triggers an immune-inflammatory response, resulting in the production of pro-inflammatory cytokines (TNF-alpha, IL-1beta, IL-6) that cause tissue damage." (PMID 37892006, 2023). "The salivary biomarkers caspase-1 and TNF-α showed high diagnostic accuracy in distinguishing periodontal health from periodontitis." (PMID 36794778, 2023). "Collectively, these findings provide a strong indication of the potential role of IL-1β and TNF-α in modulating the risk of both AD and periodontitis." (PMID 36915108, 2023). "Activation of the inflammatory response in plaque-stimulated periodontal tissues is the underlying pathological change in chronic periodontitis, and periodontal tissues release large amounts of inflammatory factors such as IL-1β, IL-6, IL-17, and TNF-α." (PMID 35942384, 2022). "Red complex bacteria and TNF-α levels are significantly associated with the aetiopathogenesis or aggravation of periodontitis and CKD." (PMID 35336824, 2022). "We evaluated the expression levels of known proinflammatory cytokines associated with periodontitis (IL-1β, IL-6, and TNF-α)." (PMID 36319994, 2022). "DM aggravated periodontal destruction in A. actinomycetemcomitans-induced periodontitis, as shown by a significant increase in TNF expression, leukocyte infiltration, and bone loss." (PMID 35052857, 2022). "This was also associated with a reduction of reduced serum IL-6, TNFα, and IL-1β in patients with periodontitis compared to baseline." (PMID 35874771, 2022). "Other clinical and animal studies reported enhanced serum levels for IFN-γ, TNF-α, and IL-10, as well as decreased IL-2 levels in patients with A. actinomycetemcomitans- and P. gingivalis-associated periodontitis." (PMID 35203495, 2022). "In chronic inflammatory diseases associated with bone destruction, such as RA and periodontitis, TNF often stimulates other cell types, such as stromal cells, synovial fibroblasts, and T cells, to aggravate pathologic bone erosion." (PMID 35798734, 2022). "An unbalanced oral microbiome causes periodontitis and systemic disease by activating proinflammatory cytokines (IL‐1, IL‐7, IL‐10, IL‐17, IL‐8, TNF‐α, and MCP‐1) and neutrophils." (PMID 35578891, 2022). "For example, CEVs released by stem cells from human exfoliated deciduous teeth (SHED-EVs) repressed IL-6 and TNF-α gene expression in bone marrow mesenchymal stem cells (BMMSCs) and prevented alveolar bone loss in mouse models of periodontitis." (PMID 36585740, 2022). "In another meta-analysis, the TNF-α-308G/A polymorphism was significantly associated with decreased risks of chronic periodontitis and aggressive periodontitis in Asians." (PMID 35454140, 2022). "The presence of H. pylori also correlates with greater colonization by periodontitis-associated bacteria in the subgingival pocket and with an increased release of pro-inflammatory cytokines, such as IL-6, IL-8 and TNFα." (PMID 35978839, 2022). "The results showed that bee venom (100 μg/kg) treatment reduced inflammatory bone loss-related periodontitis induced by P. gingivalis and reduced the expression of IL-1β and tumor necrosis factor (TNF)-α in vivo." (PMID 35624686, 2022). "Saliva from periodontitis patients caused a prominent increase in TNF-α and IL-6 levels in RAW 264.7 macrophages, and these increases were significantly mitigated by G3@SeHANs and PAMAM-G3." (PMID 36207325, 2022). "In a similar study based on a murine model of periodontitis, CEVs released from PDLSCs decreased the production of IL-18, TNF-α, and IL-1β to alleviate bone loss in periodontitis." (PMID 36585740, 2022).
periodontitis (continued). "TLR activation stimulates an intracellular signaling cascade, leading to the synthesis of pro-inflammatory mediators, including TNF and IL-1, leukocyte migration, and osteoclastogenesis, inducing bone loss and progression into periodontitis." (PMID 36362030, 2022). "Our results revealed that the downregulation of macrophage-specific Act1 aggravates periodontitis, alveolar bone loss, inflammation, M1-polarization, and TNF/NF-κB signaling." (PMID 33748112, 2021). "In a cross-sectional study, gingival fluid TNF-α levels were positively associated with blood pressure, which induces a double inflammation effect on patients concurrently suffering from periodontitis and hypertension." (PMID 34299815, 2021). "TNF-α 308 G/A polymorphism had a significant relationship in the prevention of periodontitis risk with OR (95% CI), 1.13 (0.88–1.39)." (PMID 35046930, 2021). "In periodontitis, IL‐1, IL‐6, IL‐17A, and tumor necrosis factor‐α (TNF‐α) known as pro‐inflammatory cytokines cause body immune responses to oral bacteria specifically called Porphyromonas gingivalis." (PMID 34272761, 2021). "During periodontitis development, the loss of bone tissues is closely related to the increase of TNF expression." (PMID 34790039, 2021). "A recent study reported that in the Asian population, tumor necrosis factor (TNF)-α G-308A (rs1800629) polymorphism is linked with increased susceptibility to chronic periodontitis." (PMID 34557201, 2021). "The question of this study is as follows: in aging adults, do chronic apical periodontitis lesions as biomarkers have a risk effect on the immunoexpression of pro-inflammatory cytokines (IL-1β, IL-6 and TNF-α) compared to adults?" (PMID 35053012, 2021). "Th1 cytokines are structurally related to IL-2, IFN-γ, and TNF-α, whose polymorphisms are possibly associated with periodontitis risk." (PMID 35046930, 2021). "Compared to WT mice, less alveolar bone loss, osteoclast formation, and expression of TNF-α were observed in ligation-induced periodontitis in cot/tp12-deficient (cot/tp12−/−) mice." (PMID 34445604, 2021). "In one of our included studies, the multivariate analysis showed an association between IL-6 and TNF-α in patients with AD and periodontitis." (PMID 34108875, 2021). "Previous studies demonstrated that TNFα G-308A, IL-1α C-889T and IL-1β C+3954T polymorphisms were associated with risk of chronic periodontitis." (PMID 34610045, 2021). "IL-1β, IL-6, and TNF-α are the main inflammatory cytokines of periodontitis, which contribute to inflammation and bone loss during periodontitis." (PMID 34592963, 2021). "Polymorphisms of IL-10 have been associated with those of tumor necrosis factor α IL-1α, IL-1β and IL-1RA in periodontitis." (PMID 34069916, 2021). "Clinical evidence suggested that the gingival crevicular levels of IL-1β and TNF-α are positively associated with the onset and progression of periodontitis." (PMID 33485352, 2021). "Periodontitis is associated with several host responses, including expression of IL-1β, IL-6, and TNF-α in response to oral bacteria." (PMID 34592963, 2021). "Emerging experimental and clinical studies have demonstrated that TNF-α, IL-1β, and IL-6 are associated with the initiation and progression of periodontitis." (PMID 34395635, 2021). "The inflammatory response associated with cardiovascular disease and also chronic periodontitis is modulated by proinflammatory cytokines such as TNF-α, IL-1, and IL-6." (PMID 34884653, 2021). "Several polymorphisms were associated with periodontitis, including the Fc-γ receptor, ILs-1,4,6,10,18, TNF-α, vitamin D receptor, cluster of differentiation-14, MMP-1, Toll-like receptor-2 and 4, and COX-2." (PMID 33340075, 2021). "Meta-analysis of the association between TNF-α-857C/T (rs1799724) polymorphism and chronic periodontitis." (PMID 32899013, 2020).
periodontitis (continued). "Although literature showed a lack of studies in the field of epigenetic factors related to periodontitis, a strong association has been found between IL-1B and TNF-α polymorphism and persistent apical periodontitis." (PMID 32684934, 2020). "There are data suggesting that progressive destruction of bone and connective tissue in patients with periodontitis is associated with a combination of cytokines - interleukins (IL) 1β, 6, tumor necrosis factor-α (TNF-α), and prostaglandins E2." (PMID 32742517, 2020). "For both CP and AgP, we observed the effects of TNF-α gene polymorphisms and susceptibility to periodontitis for Asians were stronger than Caucasians and Mixed." (PMID 32899013, 2020). "Meta-analysis of the association between TNF-α-1031T/C (rs1799964) polymorphism and aggressive periodontitis." (PMID 32899013, 2020). "The number of macrophages and macrophages-secreted pro-inflammatory cytokines including IL-1, IL-8, TNF-α and so on are elevated in periodontitis-associated gingival tissue biopsies." (PMID 32503416, 2020). "Meta-analysis of the association between TNF-α-308G/A (rs1800629) polymorphism and aggressive periodontitis." (PMID 32899013, 2020). "With accumulating evidence, we therefore aimed to examine the associations between TNF-α gene polymorphisms and periodontitis susceptibility by conducting an updated meta-analysis of original studies." (PMID 32899013, 2020). "To date, numerous studies evaluated the association between TNF-α gene polymorphisms and periodontitis susceptibility have been published, but the results were inconsistent." (PMID 32899013, 2020). "Meta-analysis of the association between TNF-α-1031T/C (rs1799964) polymorphism and chronic periodontitis." (PMID 32899013, 2020). "Our study was the first meta-analysis documented an association between TNF-α-1031T/C gene polymorphisms and periodontitis susceptibility." (PMID 32899013, 2020). "Further studies aiming to rate the genetic risk for periodontitis have focused on molecular levels of IL-1, IL-6, TNF-α, Vitamin-D receptor, Fc-gamma receptor, IL-10, and matrix metalloproteinase." (PMID 32684934, 2020). "Meta-analysis of the association between TNF-α-857C/T (rs1799724) polymorphism and aggressive periodontitis." (PMID 32899013, 2020). "Meta-analysis of the association between TNF-α-308G/A(rs1800629) polymorphism and chronic periodontitis." (PMID 32899013, 2020). "Meta-analysis of the association between TNF-α-863C/A (rs1800630) polymorphism and chronic periodontitis." (PMID 32899013, 2020). "According to several studies, the association between periodontitis and high levels of IL-1β, TNF-α, and MMP-8 in the GCF is well established." (PMID 32064567, 2020). "Meta-analysis of the association between TNF-α-238G/A (rs361525) polymorphism and aggressive periodontitis." (PMID 32899013, 2020). "Meta-analysis of the association between TNF-α-238G/A (rs361525) polymorphism and chronic periodontitis." (PMID 32899013, 2020). "Meta-analysis of the association between TNF-α-863C/A (rs1800630) polymorphism and aggressive periodontitis." (PMID 32899013, 2020). "IL-1Ra and IL-8 concentrations were higher in those with medium or high risk (CRS II and CRS III, p < 0.001) of periodontitis, whereas IL-10 and TNF-α concentrations were lower when compared to those with low risk (CRS I)." (PMID 31817464, 2019). "Both periodontitis and peri-implantitis have been proven to be associated with several host susceptible genes, such as interleukin-1, interleukin-6, tumor necrosis factor-alpha, and transforming growth factor beta." (PMID 31636864, 2019). "TNF-α causes tissue destruction and an erosive reaction in periodontitis, and increased TNF-α levels are known to promote cartilage collagen degradation and bone resorption." (PMID 31027223, 2019).